TAS2R12P (taste 2 receptor member 12, pseudogene)
Synonyms: T2R12; PS10; TAS2R12; TAS2R26
Gene: Transcribed processed pseudogene on chromosome 12 (10,894,943 to 10,895,882, reverse strand). Ensembl gene ENSG00000256682.
Diseases named in the same sentence as TAS2R12P in open-access papers:
TAS2R12P is named in the same sentence as 3 diseases in open-access papers, as found by Europe PMC text mining. Sharing a sentence is not in itself a finding about the gene and the disease.
TAS2R12P shares sentences with these, for which no sentence is quoted: breast carcinoma (1 paper); Hepatic steatosis (1); tumor (1).